IRS1 (insulin receptor substrate 1)
Diseases named in the same sentence as IRS1 in open-access papers (continued):
Sharing a sentence is not in itself a finding about the gene and the disease.
tumor (continued). "In BC, IRS-1 and its phosphorylated form (p-IRS1) are key mediators in the insulin and insulin-like growth factor (IGF) signalling pathways and play crucial roles in the cellular signalling pathways influencing tumour progression and treatment response." (PMID 38474001, 2024). "MMP-9 secreted from TANs may interact with insulin receptor substrate 1 (IRS-1), and further regulate the PI3K/AKT signaling pathway to contribute to the proliferation of tumor cells." (PMID 39582869, 2024). "Besides, the expression of 7 genes (EZH2, FLT1, IRS1, KDR2, MYB2, JUN, and TIMP2) was significantly different in metastatic tissue when compared with the primary tumor." (PMID 36879084, 2023). "Furthermore, extensive correlations between IRS-1 and IRS-2, RUNX3 and SMAD4 in tumor and stroma, were observed (0.15 < r < 0.60)." (PMID 36900240, 2023). "In univariate analyses, high expression levels of IRS1 in stromal cytoplasm, RUNX3 in tumor (nucleus and cytoplasm) and stroma (nucleus and cytoplasm), and SMAD4 in tumor (nucleus and cytoplasm) and stromal cytoplasm were related to increased disease-specific survival (DSS)." (PMID 36900240, 2023). "Another possible tumor-driving pathway with TNS2 includes AXL, IRS-1, and GLUT4." (PMID 35804982, 2022). "In a recent study, we demonstrated that IHZ-1 inhibits tumor growth and induces cell apoptosis through inhibiting the kinase activity of mTORC1 without activation of AKT, which is associated with JNK/IRS-1 activation." (PMID 35198445, 2022). "In addition, IGF-1R has a synergistic effect on ALK signaling due to its protein Insulin receptor substrate 1 (IRS-1) which inhibits the IGF1R/IRS1 pathway and increases the sensibility of the tumor cells to ALK targeting." (PMID 34082691, 2022). "However, the expression levels of IRS1 and NS3C1 were significantly downregulated in primary tumour tissues." (PMID 34717619, 2021). "Among them, the insulin-like growth factor 1 receptor/insulin receptor substrate 1 (IGF1R/IRS1) signaling pathway contributes to the transformation and growth of malignant cells, and enhances the migration and invasiveness of tumor cells in several types of cancers, including OC7–10." (PMID 33723215, 2021). "We also confirmed that ZJQ-24 inhibits tumor growth and induces cell apoptosis through inhibition the kinase activity of mTORC1 without activation of AKT, which is associated with JNK/IRS-1 activation." (PMID 33116125, 2020). "Additionally, IRS1 (insulin receptor substrate 1), DCN (decorin), FMOD (fibromodulin), and CXCL12 (chemokine C-X-C motif ligand 12) were down-regulated in tumor tissues." (PMID 32714651, 2020). "In addition, the authors observed the significant relationship between the tumor size of HCC and the level of IRS-1 expression." (PMID 32695243, 2020). "The re-biopsied tumour at resistance was PIK3CA wt but had low PIK3R1 expression and acquired an IRS1 P313S variant that was not present in the sensitive tumour." (PMID 31653970, 2019). "Finally, as an insulin feedback was reported to limit the efficacy of PI3K inhibition in several tumor models, we checked for the effects of the combined PIK‐75 plus vemurafenib therapy on the expression of the IRS‐1." (PMID 31115969, 2019). "Indeed, the mRNA and protein expression of IGF1R, IRS1, and GRB10 was increased in Gr-1+CD11b+ cells sorted from spleens of 4T1 tumor-bearing mice compared with that from healthy control mice." (PMID 29973593, 2018). "Here we focused on the correlation of myeloid IGF1R, IRS1, and GRB10 with human tumor progression." (PMID 29973593, 2018). "However, in light of our findings, IRS1 most likely still requires activation by RTKs, such as the IGF1 receptor, in these tumours." (PMID 27876799, 2016). "Moreover, in addition to p85β (PIK3R2) and Sox2, IRS1, VEGF and CXCR4 have been reported to be target genes of miR-126-3p and to participate in miR-126-3p-induced tumor suppression." (PMID 27191494, 2016).
tumor (continued). "Tumor samples with mutations in PF00613, on the other hand, have higher IRS1 levels and no changes in Akt phosphorylation status." (PMID 25568936, 2015). "It has been reported that miR-148a inhibits tumor metastasis by targeting IGF-IR and IRS1." (PMID 25928008, 2015). "Negative feedback loop of mTORC1/p70S6K towards IRS-1/PI3K signaling resulting in increased mTORC2 activity has been well described mainly in tumor cells." (PMID 25880554, 2015). "The tumor suppressive role of klotho may be initiated by downregulation of IGF-1 receptor phosphorylation, and subsequent decreases in IRS-1, PI3K, Akt, and mTOR phosphorylation." (PMID 23432957, 2013). "IRS1 expression did not significantly differ in relation to age at diagnosis, gender, tumor location (right versus left colon), Duke's stage, and MSI status." (PMID 22558377, 2012). "Moreover transgenic overexpression of IRS-1 or IRS-2 in the mammary gland results in hyperplasia, tumor development and metastasis." (PMID 19534786, 2009). "Neither the IR nor the IRS-1 staining levels showed any correlation with tumor grade advancement (data not shown)." (PMID 17233921, 2007). "In addition, upregulation of p‐AKT in Exos‐treated tumours was reversed by BKM120, whereas downregulation of KLF13 and upregulation of miR‐3126‐5p, SH2B1, IRS1, and p‐PI3K caused by Exos were not affected by BKM120 co‐administration." (PMID 41410190, 2025). "Notably, IRS-1 and IRS-2 are upregulated in HCC and actively support the tumour phenotype." (PMID 38710924, 2024). "Moreover, in two of three validated cases we observed that tumor cells in the combination treatment group lacked nuclear IRS-1 staining while all other treatment arms had discernable nuclear accumulation of IRS-1." (PMID 33082316, 2020). "Alternatively, IRS-1 and IRS-2 may independently regulate their functional outcomes through the formation of unique scaffolding interactions, with the ability of IRS-2 to promote tumor progression being dominant to the suppressive activity of IRS-1." (PMID 31393907, 2019). "For a more comprehensive understanding of the characteristics of tumors lacking in Irs1, we conducted gene expression microarray analysis to compare the tumor expression profiles of genes in the DEN-treated LIrs1KO mice as compared to the DEN-treated control mice." (PMID 28710407, 2017). "In addition, higher expression of phosphorylated insulin receptor substrate 1 (pIRS-1) was detected in these tumour tissues than in adjacent non-tumour tissues and negatively correlated with survival rates of patients with these cancers." (PMID 26268733, 2015). "The distinct functions of IRS-1 and IRS-2 in tumor progression may reflect a differential sensitivity of IRS-1 and IRS-2 to the effects of negative feedback regulation, which could alter the longevity and intensity of signals initiated through each adaptor protein." (PMID 19534786, 2009). "Interestingly, IRS1 was significantly up-regulated in the benign and LMP tumours of our study." (PMID 15471544, 2004). "Additionally, prospective evaluation of the contribution of IRS1/2 overexpression to patient outcomes and tumor aggressiveness in the absence of RTK treatment could further elucidate the mechanistic specificity of these amplifications in patient tumors." (PMID 32669109, 2020). "More broadly, in ΔNp63 overexpressing SSC tumours, unbalanced expression of the TAp63/ΔNp63 isoforms may lead to enhanced Igf-r1/Irs1 transcriptional activation, resulting in augmented protein abundance of IGFR1 and IRS1, which may increase sensitivity of cancer cells to growth factor stimulation." (PMID 30594912, 2018). "Furthermore, NE can enzymatically degrade insulin receptor substrate-1 (IRS-1) and then increase the interactions of phosphatidylinositol 3-kinase (PI3K) and the potent mitogen platelet-derived growth factor receptor (PDGF), triggering to tumor cell proliferation." (PMID 24457622, 2014).
tumor (continued). "For instance, mTOR inhibition can promote negative feedback in which S6K is able to phosphorylate Insulin receptor substrate 1 (IRS1) with the subsequent activation of PI3K and tumor growth." (PMID 37237486, 2023). "During anti-tumor treatment, blocking mTORC1 with RAPA will up-regulate PI3K/Akt activity upstream of mTORC1 through the IRS-1 negative feedback loop." (PMID 30982374, 2019). "Other important molecules involved in the IGF-1 signalling pathway, such as IRS-1, IGF-1 receptor, pAKT and AKT did not change significantly in relation to the size of the tumour." (PMID 30410539, 2018). "However, expression levels of FABP1, CD36, IRS1, THBS1, and TGFB1 did not significantly differ in various tumor stages." (PMID 36193307, 2022). "It is likely that a suite of biomarkers, both in the host and tumor will be required rather than single biomarker selection, with some candidates for study in RMS including IGF2, pIGF1R/IGF1R, IGF1, pIRS-1/IRS-1, pIR-A/IR-A, IGFBP-6, and maybe others such as HSPs, PDGFR and Erb2." (PMID 21437217, 2011).
cancer (203 papers, 2007 to 2025). A tumor composed of atypical neoplastic, often pleomorphic cells that invade other tissues. "Insulin receptor substrate 1 (IRS1), an adaptor protein of insulin signaling pathways, is associated with the progression of many inflammation-related cancers." (PMID 36768755, 2023). "As CCA is one of the cancers associated with oxidative stress, we investigated the association between oxidative stress and IRS1 expression in CCA." (PMID 36768755, 2023). "Acting as an adaptor protein that conveys signals originating from different receptors to multiple downstream signalling molecules, IRS1 represents a potentially relevant predictive clinical biomarkers for cancers susceptible to IGF-IR targeting." (PMID 30594912, 2018). "The activation of IGF-1R upon ligand binding induces phosphorylation of an adopter protein insulin receptor substrate-1 (IRS-1) which is also linked to various cancer subtypes." (PMID 29787591, 2018). "IRS1 plays a central role in cancer cell proliferation, in contrast, IRS2 is associated with cancer cell motility and metastasis." (PMID 24497996, 2014). "So far, in the nucleus, it has been reported that IRS-1 regulates transcription of rRNA and several genes implicated in cell proliferation and cancer progression." (PMID 24624118, 2014). "Numerous studies have revealed that IRS1 is implicated in cancer progression." (PMID 36768755, 2023). "Some variations in IRS1 have been reported to be related to increased cancer risk." (PMID 34805171, 2021). "IRS1 has also been implicated in cancer initiation and progression." (PMID 32669109, 2020). "Collectively, we have shown the biological impact of newly identified mutationswithin the IRS1 gene and suggest that these mutations may be diagnostic markers inlung cancers." (PMID 30807634, 2019). "In other cancer types, this is associated with inhibitory phosphorylation of the signaling adapter, insulin receptor substrate-1 (IRS-1) and inhibition of the downstream PI3K/Akt/mTOR and mitogen-activated protein-kinase/extracellular signal-regulated kinase (MAPK/ERK) pathways." (PMID 30211120, 2018). "We further speculate that the interaction of Axl and TNS2 could be a potential therapeutic target for the management of the IRS-1-associated cancer progression and other related diseases." (PMID 30419905, 2018). "The interaction of Axl and TNS2 could serve as a potential therapeutic target for the management of the IRS-1-associated cancer progression and other related diseases." (PMID 30419905, 2018). "Moreover, miR-145 may inhibit cancer cell proliferation by targeting genes associated with growth factors, including IRS-1, IGF-IR, or epidermal growth factor receptor (EGFR)." (PMID 39896297, 2025). "Furthermore, miR-410-3p inhibits IRS-1, blocking adipocyte differentiation and regulating lipid metabolism, and may contribute to fat loss in cancer-associated cachexia." (PMID 40504789, 2025). "NE translocates to cancer cells, degrades IRS1, and activates PI3K signalling to directly stimulate proliferation." (PMID 41451221, 2025). "Molecular investigations further elucidate that miR167a suppresses the activation of the PI3K‐AKT pathway by targeting insulin receptor substrate 1 (IRS1), leading to inhibition of cancer cell proliferation and induction of apoptosis." (PMID 40452566, 2025). "Extensive research has shown that IRS1 is involved in the occurrence and development of various cancers, including LC." (PMID 39422696, 2024). "Yet, in cancer the PI3K signalling pathway is overactivated, associated with increased tyrosine and reduced serine phosphorylation of IRS1." (PMID 39469929, 2024). "IRS-1/-2 is also expressed in some cancer cell lines, and its high expression has roles in cancer initiation and progression." (PMID 37894751, 2023).
cancer (continued). "IRS1 has been discovered in the nucleus of cancer cells, where it plays synergistic roles with IRS1 in the cytoplasm to stimulate cell cycle progression, DNA repair, cell proliferation, and estrogen responsiveness." (PMID 36768755, 2023). "IRS-2 is generally related to processes such as metastasis, migration, and cell invasion in different types of cancer, while IRS-1 is related to proliferation." (PMID 36975518, 2023). "The PKA can interact with downstream IRS-1 to activate the PI3K/AKT/mTOR pathway related to cancer cell survival, proliferation, and growth." (PMID 35798765, 2022). "Neutrophils have been shown to promote cancer progress via degradation of insulin receptor substrate-1 (IRS-1)." (PMID 35327484, 2022). "For instance, neutrophil elastase (NE), stored into neutrophil azurophil granules, can induce cancer cells proliferation via the degradation of insulin receptor substrate 1 (IRS-1), an inhibitor of phosphoinositide 3-kinase (PI3K)." (PMID 35158948, 2022). "It has been reported to inhibit cancer cell proliferation by modulating the expression of insulin receptor substrate-1 (IRS1) and insulin-like growth factor receptor-1 (IGF1R)." (PMID 35883653, 2022). "Here, the changes of three key molecules (IRS1, JUN and GSK3B) in the cancer-associated pathways were verified by real-time PCR and Western blotting." (PMID 36446361, 2022). "Among cancer-related genes, CARD11(18%) and IRS1(18%) were the most common somatic mutated genes, followed by PSMD11, RELN, RRAS2, SMC1A, SYNE1 and ZFHX3, and the mutation rates of the latter six genes were all 14%." (PMID 36457486, 2022). "IRS1 is an important signaling protein that participates in the regulation of important cancer-related pathways, such as the PI3K/AKT signaling pathway." (PMID 35387129, 2022). "It has been reported that miR-126 can target insulin receptor substrate 1 to suppress the invasion and migration of cancer cells." (PMID 34256796, 2021). "The specific expression and function of IRS-1 in human cancer has aroused our continuous attention to follow-up trials." (PMID 34443299, 2021). "The function of NE on cancer cell proliferation happens after it entry into the cancer cell cytoplasm and cleavage the IRS-1 to active the PI3K–AKT proliferation pathway." (PMID 34681796, 2021). "Lastly, some genes (HMGN5, IRS1, PHGDH, MXRA5, GOLIM4, and SFRP2) are associated with the development of multiple cancer types." (PMID 33924951, 2021). "The level of IRS1 is highly increased in proliferative cells such as human and mouse cancer cells, whereas profoundly decreased in differentiated cells." (PMID 33763030, 2021). "It is reported that IRS1 plays a key role in cancer cell proliferation and mediates the resistance to anticancer drugs, while IRS2 acts mainly in cancer cell motility and metastasis." (PMID 34093789, 2021). "Phosphorylation of mTORC1 initiates subsequent negative feedback mechanisms, such as serine/threonine phosphorylation of IRS-1, which are lost in a cancer phenotype." (PMID 32655497, 2020). "Even if true, preclinical evidence suggests one can enhance mTORi-mediated anti-cancer effects by blocking the proximal activation of IRS-1, PI3K, or Akt." (PMID 32630797, 2020). "In particular, mTOR inhibition induced insulin receptor substrate 1 (IRS-1) expression and abrogated feedback inhibition of the pathway, leading to Akt activation in cancer cell lines and in primary cell cultures." (PMID 32748870, 2020). "Around the same time, derepression of IRS-1—immediately downstream of IGF-1R—was described as a potent mechanism used by cancer cells to quickly evade single-agent mTORi." (PMID 32630797, 2020). "For example, miR-126, which is an angiogenesis inducer, regulates cancer metabolism via its downstream target insulin receptor substrate-1 (IRS1)." (PMID 32121073, 2020). "IRS-1 has been shown to play a pivotal role in cancer cell proliferation and BRAFi therapy resistance and upregulation is observed in many malignancies." (PMID 33082316, 2020).